TREM2 (triggering receptor expressed on myeloid cells 2)
Diseases named in the same sentence as TREM2 in open-access papers (continued):
Sharing a sentence is not in itself a finding about the gene and the disease.
COVID-19 (12 papers, 2021 to 2025). A disease caused by infection with severe acute respiratory syndrome coronavirus 2. "In macrophages derived from patients with COVID-19, high levels of TREM-2 and TMPRSS2 mRNA, was associated with higher hypoxia scores, implying poor overall survival of these patients." (PMID 36211412, 2022). "We also asked if microglia in COVID-19 brains expressed more TREM2 compared to microglia in ARDS in the ION." (PMID 37483351, 2023). "TREM-2 mRNA expression was substantially up-regulated in the PBMCs of patients with COVID-19 compared with the healthy group, while expression of TREM-1, TLT1, TLT2, and TLT4 was slightly increased." (PMID 34878838, 2021). "TREM-2 mRNA expression was increased on PBMCs from patients with COVID-19 compared to healthy donors, with the highest abundance in patients with severe COVID-19." (PMID 34878838, 2021). "Here, we identified SARS-CoV-2 M protein as a novel exogenous ligand of TREM-2 by immunofluorescence, co-IP, and in vitro binding assay both in 293T cell, primary T cells, and the lung tissue of patients with COVID-19." (PMID 34878838, 2021). "Among patients with severe COVID-19, TREM-2 mRNA expression was highly induced when patients were under critical conditions (in ICU) compared to when before and after ICU care (pre-ICU and post-ICU)." (PMID 34878838, 2021). "Together, these results indicated a potential role of TREM-2 in the CD4+ T cell responses in patients with COVID-19." (PMID 34878838, 2021). "As the expression of TREM-2 on CD4+ T cells of patients significantly increased, we then focused on the role of TREM-2–expressing CD4+ T cells in COVID-19 in the following experiments." (PMID 34878838, 2021). "GO and KEGG pathway analyses showed that inflammation-, immunity-, and infection-associated terms were enriched in db/db mice microglia, such as Il17ra, Il6ra, Cmklr1, Nlrp3, Trem2, Coronavirus disease-COVID-19, Epstein-Barr virus infection, phagosome and NF-κB signaling pathway." (PMID 35721719, 2022). "TREM-2 was up-regulated in periphery and lung-infiltrating T cells from patients with COVID-19." (PMID 34878838, 2021). "Furthermore, the binding of M protein and TREM-2/CD3ζ/ZAP70 complex was confirmed by IP in COVID-19 lung, which was accumulated with abundant TREM-2+CD4+ T cells." (PMID 34878838, 2021). "Higher levels of phosphorylated CD3ζ (Tyr83) and ZAP70 (Tyr319) were detected in pseudovirus–M protein–stimulated TREM-2+CD4+ T cells from patients with COVID-19 compared with TREM-2− groups, whereas pseudovirus vector did not induce the phosphorylations of CD3ζ and ZAP70 in TREM-2+CD4+T cells." (PMID 34878838, 2021). "We next assessed the signal transduction mediated by TREM-2 in T cells from patients with COVID-19." (PMID 34878838, 2021). "In summary, the present study explored the role of TREM-2 on T cells in COVID-19." (PMID 34878838, 2021). "In addition, the MFI of TREM-2 in COVID-19 lung was significantly higher than these in healthy lung." (PMID 34878838, 2021). "Mass spectrum identified an immunoreceptor tyrosine-based activation motif (ITAM) adaptor CD3ζ (CD247), which is a component of TCR complex to assist with T cell antigen recognition, as a potential protein that interacted with TREM-2 in patients with COVID-19 T cells." (PMID 34878838, 2021). "In parallel, a recent report showed enhanced TREM2 protein levels in the CSF of a patient with COVID-19-associated encephalopathy, along with increased protein levels of IL6, IL8, and TNF in both CSF and serum (see section “Microglia Respond to the Systemic Inflammatory Response in COVID-19”)." (PMID 33737867, 2021). "However, TREM-2 expression was up-regulated in T cells upon the treatment of plasma from patients with COVID-19, which together indicate that some plasma components such as inflammatory cytokines may induce TREM-2 expression in patients with COVID-19." (PMID 34878838, 2021). "Hence TREM-2 may be involved in lung localised CD4+ T cells in COVID-19 patients." (PMID 36211412, 2022).
COVID-19 (continued). "TREM2+ DCs, which play a role in T-cell priming and are found in the BALF of severe COVID-19 patients, were enriched in the classical signature, but depleted in the CRS signature." (PMID 35438176, 2022). "Together, our data suggested that TREM-2 promoted TH1 and cytotoxic responses of T cells in patients with COVID-19." (PMID 34878838, 2021). "In this study, we demonstrated that TREM-2 was inducibly expressed on T cells in response to SARS-CoV-2 infection and substantially elevated in patients with severe COVID-19." (PMID 34878838, 2021). "In the present study, TREM-2 interacted with CD3ζ/ZAP70 complex in T cells, and this interaction was strengthened in patients with COVID-19 compared to healthy donors." (PMID 34878838, 2021). "We found that triggering receptor expressed on myeloid cells 2 (TREM-2) was induced in T cells in the blood and lungs of patients with COVID-19." (PMID 34878838, 2021). "Together, these data suggested that TREM-2 bound to SARS-CoV-2 M protein and interacted with CD3ζ/ZAP70 complex in T cells during COVID-19." (PMID 34878838, 2021). "We found that M protein bound to TREM-2/CD3ζ/ZAP70 complex, and this binding was increased in the lung of patients with COVID-19 versus healthy controls." (PMID 34878838, 2021). "Immunofluorescence microscopy was conducted to reveal the localisation of TREM-2 in CD4+ T cells in lung tissue of non-severe COVID-19 patients." (PMID 36211412, 2022). "Moreover, we found that the binding of TREM-2 and CD3ζ/ZAP70 complex was enhanced in T cells of patients with COVID-19 versus healthy controls and increased in T cells from severe versus nonsevere patients." (PMID 34878838, 2021). "This could explain why we detected the binding of M protein with TREM-2 and CD3ζ as well as ZAP70 in the lung tissue of patients with COVID-19, where abundant infiltrating TREM-2+CD4+ T cells were found." (PMID 34878838, 2021). "Furthermore, TREM-2 mRNA expression on PBMCs was analyzed in patients with nonsevere and severe COVID-19, as well as patients admitted to the intensive care unit (ICU)." (PMID 34878838, 2021). "TREM-2–Fc fusion protein, used to block the interaction between TREM-2 and M protein, reduced the phosphorylation of CD3ζ (Tyr83) and ZAP70 (Tyr319) in CD4+ T cells of patients with COVID-19 upon pseudovirus–M protein stimulation, whereas control IgG did not affect the phosphorylation of CD3ζ/ZAP70." (PMID 34878838, 2021). "Furthermore, we found that anti-CD3 agonist Abs could not induce TREM-2 up-regulation in T cells, which indicated that TREM-2 expression was increased in COVID-19 T cells independent of TCR stimulation." (PMID 34878838, 2021).
injury (12 papers, 2014 to 2025). Damage inflicted on the body as the direct or indirect result of an external force, with or without disruption of structural continuity. "Previous studies have found increased gene expression of TREM2 following traumatic brain injury, and in former American football players, higher levels of soluble Trem2 were associated with higher tau concentrations in the CSF." (PMID 41264095, 2025). "In this study, we explored whether resveratrol could ameliorate neuroinflammation and produce anti-mechanical allodynia effects via regulating TREM2 in spared nerve injury rats, as well as investigated the underlying mechanisms." (PMID 33081801, 2020). "Recent studies illuminate that Rhein fosters M2 polarization in macrophages by targeting the NFATc1/TREM2 pathway, a mechanism pivotal in regulating the inflammatory response and prognosis following acute lung injury." (PMID 40552184, 2025). "In particular, it has been suggested that increased levels of TREM-2, which is primarily expressed in the brain by microglia, facilitates recovery from brain injury." (PMID 35723306, 2022). "A previous study also suggested that the balance of TREM-1 and TREM-2 regulated the progression of acute lung injury." (PMID 34176389, 2021). "Although the relationship between TYROBP and ferroptosis has not yet been fully elucidated, a mouse model of lipopolysaccharide-induced acute lung injury revealed that TREM2 can inhibit DAP12 expression and reduce ferritin accumulation, thereby inhibiting macrophage ferroptosis." (PMID 40895546, 2025).
nonalcoholic steatohepatitis (12 papers, 2022 to 2026). "A recent study revealed that TGF-β signaling is involved in the development of nonalcoholic steatohepatitis-associated macrophages (NAMs), which express molecular markers, including TREM2, in the liver." (PMID 39838454, 2025). "In the liver of patients with metabolic dysfunction-associated steatohepatitis (MASH), TGF-β, among other molecules, has been identified as a crucial regulator of disease-associated expansion of TREM2 + macrophages." (PMID 41472730, 2025). "In the liver, Trem2-positive macrophages were shown to be responsible for the clearance of apoptotic hepatocytes, which prevented non-alcoholic steatohepatitis development." (PMID 38360943, 2024). "Moreover, a nonalcoholic steatohepatitis (NASH)-related diet induces the collaboration of Atf3 with LXRs to induce Trem2 and Cd9 expression, promoting the establishment of the SAM and/or LAM phenotypes." (PMID 35359989, 2022). "In nonalcoholic steatohepatitis (NASH), TREM2 promoted the ability of macrophages to clear apoptotic cells, limiting the deterioration of NASH." (PMID 39497214, 2024).
prion disease (12 papers, 2016 to 2025). A transmissible disease that is caused by a protein that is able to induce abnormal folding of normal cellular proteins, leading to characteristic spongiform brain changes, which are associated with neuronal loss without an inflammatory response. "We set out to establish whether loss of TREM2 had any disease-modifying effects on the progression of prion disease." (PMID 40400621, 2025). "In contrast, TREM2 deficiency has only a modest influence on CNS prion disease." (PMID 35875357, 2022). "Next, transcriptome analysis by microarray was used to explore candidate mechanisms and identify potential molecular pathways that may contribute to the effects of Trem2 deficiency on the aggravated neuronal pathology and reduced microglial reactivity observed during CNS prion disease." (PMID 40400621, 2025). "Prion diseases are characterised by the accumulation of misfolded prion proteins and provide a highly tractable platform to determine if TREM2 has disease-modifying effects." (PMID 40400621, 2025). "We used the ME7 prion disease model to assess the role of TREM2 in the progression and pathology of neurodegenerative disease." (PMID 40400621, 2025). "Genes involved in myelination and axon ensheathment tend to have higher expression in the Trem2−/− NBH group but decreased expression in Trem2−/− mice inoculated with prion disease (Mbp, Plp1, Mog, Mag, Mal, and Mobp)." (PMID 40400621, 2025). "Although the accumulation of prion disease-specific PrP was similar in the brains of mice from each group, the severity of neuropathology was increased in Trem2−/− mice." (PMID 40400621, 2025). "To explore the effect of the Trem2 genotype on prion disease, we compared the gene expression profiles of prion-infected Trem2−/− and prion-infected WT mice, identifying 170 DEGs (p < 0.005)." (PMID 40400621, 2025). "We conclude that comparative study of TREM2 in brain and biological fluids of prion diseases reveals TREM2 to be altered in human prion diseases with a potential value in target engagement, patient stratification, and disease monitoring." (PMID 33881612, 2021). "In the present study, we report TREM2 expression and levels in the brain and biological fluids of prion diseases, with special focus on sCJD, uncovering its potential role as a diagnostic marker." (PMID 33881612, 2021). "TREM2 expression in brain and biological fluids of human prion diseases and its potential role as a candidate biomarker of prion pathogenesis have not been explored." (PMID 33881612, 2021). "CSF TREM2 concentrations were assessed in HC, ND, prion diseases from sporadic, genetic and acquired aetiology, AD, and MS." (PMID 33881612, 2021). "The role of TREM2 in prion diseases, a group of rapidly progressive dementias remains to be elucidated." (PMID 33881612, 2021). "Triggering receptor expressed in myeloid cells-2 (TREM2) also contributes to the phagocytosis of apoptotic neurons and is upregulated in microglia during prion disease." (PMID 33023255, 2020). "Deeper quantification of microglial features (% area coverage and size) in the vulnerable hippocampal CA1 region substantiated an interaction between prion disease and genotype with significantly less coverage and smaller cell size in prion-infected Trem2−/− compared to WT mice." (PMID 40400621, 2025). "In the present study, we analysed the expression of TREM2 and its main sheddase ADAM10 in the brain of sporadic Creutzfeldt-Jakob disease (sCJD) patients and evaluated the role of CSF and plasma sTREM2 as a potential diagnostic marker of prion disease." (PMID 33881612, 2021). "Together with the discrepant observations of TREM2 in AD and prion disease, this study suggests that microglia-mediated phagocytosis and clearance of Aβ and prion may adopt distinct molecular pathways." (PMID 33758958, 2021).
prion disease (continued). "In addition, we analysed Sirpa, Cd47, Aif1, Trem2 and Mfge8 mRNA levels selectively in hippocampus and cerebellum at different time points during the progression of prion disease using RNA sequencing." (PMID 28545141, 2017). "Studies with models of mice with the prion disease showed that the expression of TREM 2 in microglia was increased by prion infection, but prion-infected TREM2−/− mice have reduced microglial activation." (PMID 34751640, 2021). "WT mice and Trem2−/− mice were injected with prions or NBH as a control, and brains were collected during the pre-clinical phase at 90 days after infection when only limited histopathological signs of prion disease were evident in the brain." (PMID 40400621, 2025). "To further understand the role of Trem2 in the development of neurodegenerative disease, we used a well-established prion disease model, the ME7 scrapie strain, which, unlike many other disease models, develops overt neuronal pathology." (PMID 40400621, 2025). "Here, IFNAR1 deficiency did not impact upon Il1b mRNA levels and decreased Il10 and Trem2 expression suggesting that canonical IFNAR‐STAT1/2 signaling is dominant in ME7 prion disease." (PMID 30680794, 2019). "Furthermore, deletion of Trem2 or ApoE in mice does not affect prion pathogenesis or PrPSc accumulation, suggesting that TREM2-APOE microglia signaling described in other neurodegenerative disease models does not influence prion disease." (PMID 32381108, 2020). "In the context of prion disease, TREM2 has been demonstrated to be up-regulated after prion infection, but the depletion of TREM2 did neither change incubation time and survival, nor microglia immune phenotype during prion disease." (PMID 28690540, 2017). "Therefore, TREM2 is seen as a key feature of the microglial response to neurotoxic lesions, thus having a role in neural response to infection by prions, but there are still no consistent findings that directly relate it to prion disease." (PMID 34751640, 2021). "We previously showed ME7 prion disease results in decreased Luxol fast blue myelin staining; however, we did not observe any differences in LFB staining between Trem2−/− and WT prion-infected mice, suggesting more subtle features of myelin structure/function may warrant investigation in the future." (PMID 40400621, 2025).
viral infection (12 papers, 2017 to 2024). "In the discussion, APOE and TREM2 have been implicated in susceptibility to various viral infections (such as HIV and SARS-CoV-2)." (PMID 37962454, 2024). "However, the current evidence remains insufficient for establishing a clear association between APOE or TREM2 as predictive factors for AD and specific viral infections." (PMID 37962454, 2024). "It is plausible that genetic mutations and exposure to viral infection may initiate inflammatory cascades upstream of AD pathogenesis, much like the potential mechanisms controlling TREM2 dysfunction." (PMID 39459844, 2024). "Several studies reported that TREM-2 exhibits a distinct role in virus infection in vivo, which indicated that different mechanism participated in TREM-2–mediated viral immunity." (PMID 34878838, 2021). "Taken together, these data demonstrate that TREM2 knockdown decreases cytokine-mediated CD163 expression to inhibit virus infection via Syk/PI3K and TLR4/NF-κB signaling." (PMID 32401783, 2020). "Previous studies suggested a link between virus-perturbed lipids and TREM2 that modulates pathogenesis upon viral infection, suggesting a possible link between the ApoE-TREM2 pathway and activation of HHV-6A-infected microglial cells." (PMID 31831060, 2019). "This experiment indicated that WT and Trem2−/− mice mount similar CD8 T cell responses upon viral infection." (PMID 28900132, 2017). "T cell accumulation and anti-viral function in the MHV–JHM-infected CNS were also not affected by Trem2 deficiency, suggesting that Trem2 does not overtly affect T cell activation in viral infections." (PMID 36333761, 2022). "While animal models of AD and MS support a disease attenuating role of Trem2 expressing microglia, studies examining a role of Trem2 during viral infections, which rely on proinflammatory factors for viral control, reveal context dependent protective as well as pathogenic functions." (PMID 36333761, 2022). "Several studies have reported that TREM-2 exhibits distinct roles in viral infection." (PMID 34878838, 2021). "Thus, Gal-3, TLR4, and TREM2 have a potentially major role in lung fibrosis post-viral infection." (PMID 38540252, 2024). "Moreover, Trem2−/− mice exhibited lower serum concentrations of two alternative parameters for liver damage, alkaline phosphatase (AP) and bilirubin, compared to WT mice upon viral infection." (PMID 28900132, 2017). "TREM2 hinders macrophage apoptosis, leading to chronic lung inflammation, while the TLR family participates in the immune response against the viral infection, inducing the synthesis of pro-inflammatory factors." (PMID 38540252, 2024). "This indicates differential cues for Trem2/Dap12 signaling in microglia and BMDM in the same environment during virus infection." (PMID 36333761, 2022). "In contrast, the downregulation of TREM2 and PICALM gene products increases AD risks but may promote viral infections." (PMID 37962454, 2024). "Although oligomeric Aβ can induce sTREM2 shedding and viral infections such as HIV increased levels of sTREM2 in the CSF, conditions that modulate sTREM2 shedding from full-length TREM2 are not fully understood and may occur to block the activity of full-length TREM2 and its downstream signaling." (PMID 36002854, 2022). "To demonstrate that TREM2 knockdown reduces cytokine-mediated CD163 expression to inhibit virus infection via Syk/PI3K and TLR4/NF-κB signaling, we first explored whether TREM2 knockdown promotes the expression of proinflammatory cytokines and type I interferons via these pathways." (PMID 32401783, 2020).